KCNQ1 (potassium voltage-gated channel subfamily Q member 1)
Diseases named in the same sentence as KCNQ1 in open-access papers (continued):
Sharing a sentence is not in itself a finding about the gene and the disease.
long QT syndrome (continued). "In previous studies, we have shown that KCNE1-KCNQ1 channel open-state is stabilized by PIP2 and impairment of this stabilization by arginine neutralization at position 243, 539 or 555 in KCNQ1 is correlated with the long QT syndrome." (PMID 24681627, 2014). "Determination of the number of mRNA copies of KCNQ1 (LQTS1) and KCNH2 (LQTS2) was supposed to confirm the presence of the long-QT syndrome in the group of patients from the families in whom the syndrome has been previously diagnosed on the basis of supraventricular arrhythmia by ECG." (PMID 23936797, 2013). "Interestingly, an association between epilepsy and long QT syndrome (LQTS) has been proposed for mutations in KCNQ1; however, ataxia is, to the best of our knowledge, not part of the disease spectrum associated with KCNQ1 mutations." (PMID 29527639, 2018). "According to previous KCNQ1 (potassium channel, voltage gated, KQT-like subfamily, member 1) gene screening studies, missense variants, but not nonsense or frame-shift variants, cause the majority of long QT syndrome (LQTS; Romano-Ward syndrome [RWS]) 1 cases." (PMID 28595573, 2017).
type 2 diabetes (91 papers, 2009 to 2026). "The rs2237892 SNP at the KCNQ1 locus was previously shown to display parent-of-origin effects on type 2 diabetes risk and insulin secretion." (PMID 40175764, 2025). "The gene most often included in the scores was KCNQ1, which encodes the pore-forming α subunit of voltage-gated potassium channels and was initially identified as a type 2 diabetes susceptibility gene." (PMID 38039081, 2024). "Epigenetic regulation of KCNQ1 expression is important because KCNQ1 is a risk gene that mediates susceptibility to type 2 diabetes." (PMID 39055936, 2024). "For example, KCNQ1 rs2237892 was found to be associated with infant postnatal rapid weight gain, and contributed to the risk of type 2 diabetes mellitus and its related complications." (PMID 38807370, 2024). "Twenty-five of these were previously reported type 2 diabetes-associated variants, including those consistently identified in multiple populations (e.g. variants at KCNQ1 and TCF7L2) and others enriched in the Latino population (e.g. variants at SLC16A11)." (PMID 37148359, 2023). "The top genetic association signal for type 2 diabetes (T2D) in Southwestern American Indians maps to intron 15 of KCNQ1, an imprinted gene." (PMID 35563754, 2022). "Another study showed, by identifying temporal differences in the imprinting status and methylation effects, that the intronic KCNQ1 locus mediates susceptibility to type-2 diabetes." (PMID 35163587, 2022). "Numerous studies have examined the polymorphisms in the KCNJ11 and KCNQ1 genes as the risk factors for type 2 diabetes mellitus; nevertheless, the results of the studies are inconsistent and are different in various populations." (PMID 35893051, 2022). "Several GWAS have uncovered many independent intronic regions in KCNQ1 that harbor type 2 diabetes mellitus risk alleles (rs231362, rs2283228, rs2237892, rs2237895, and rs2237897) in Europeans, East Asians, and Native Americans." (PMID 33336302, 2021). "Among these effector genes are ABCC8, KCNJ11, PDX1, ADCY5, and KCNQ1, which are recognized as pancreatic β-cell genes strongly associated with type 2 diabetes." (PMID 34425882, 2021). "The purpose of our study was to provide further insight into the potential association between KCNQ1 rs2237892 polymorphism and the risk of type 2 diabetes mellitus." (PMID 34238370, 2021). "Our meta-analysis demonstrated significant evidence to support the association between KCNQ1 rs2237892 polymorphism and predisposition to type 2 diabetes mellitus." (PMID 34238370, 2021). "Previous studies have analyzed the potential effect of KCNQ1 rs2237892 polymorphism on the predisposition to type 2 diabetes mellitus, but the findings are inconclusive and the subject of debate." (PMID 34238370, 2021). "A variant in KCNQ1 (rs163184) was found to be associated with a smaller reduction in HbA1c after 6 months of newly onset DPP-4i therapy in type 2 diabetes patients (0.3% reduction in response per each G allele)." (PMID 33594477, 2021). "Second, some type 2 diabetes genetic variants have a paradoxical association with the classically defined metabolic features of type 2 diabetes (e.g. a variant in KCNQ1 is associated with both hyperglycaemia and hypoinsulinaemia)." (PMID 32705315, 2020). "(iii) KCNJ11 (rs5210) and KCNQ1 (rs2237895) gene variants are significantly associated with type 2 diabetes in the Indian population." (PMID 33101408, 2020). "KCNQ1 has been widely reported to be associated with body mass index and other anthropometric measures, and also with type 2 diabetes mellitus in several populations." (PMID 31784582, 2019). "Further work is needed to confirm the association between KCNQ1 SNPs and insulin sensitivity, and to test any association between genotype and overt type 2 diabetes in other study populations." (PMID 30641161, 2019). "A number of SNPs at the 11p15 locus (which includes KCNQ1) have recently been implicated in type 2 diabetes in both European and Asian populations." (PMID 30641161, 2019).
type 2 diabetes (continued). "Common variation in KCNQ1 has been shown to increase susceptibility to type 2 diabetes across populations of different ethnic backgrounds." (PMID 30641161, 2019). "The majority of studies linking KCNQ1 with insulin secretion defects and type 2 diabetes risk have focused upon patients with type 2 diabetes." (PMID 30641161, 2019). "So far, five African-American type 2 diabetes-associated signals have been reported, three of which (two in KCNQ1 and one in HMGA2) were first reported in Europeans and two (INS-IGF2 and HLA-B) were first reported in African-Americans." (PMID 31049640, 2019). "Previous studies with type 2 diabetes risk genes suggested an association between KCNQ1 rs2237892 and NODAT." (PMID 31623129, 2019). "In an earlier study, KCNQ1 rs2237895 C minor allele carriers demonstrated less favorable response to rosiglitazone therapy in patients treated for type 2 diabetes." (PMID 30065651, 2018). "First, it has been shown that certain variants in the KCNQ1 gene leads to impaired pancreatic β-cell function with increased risk of future type 2 diabetes." (PMID 29259974, 2017). "A genome-wide association study examined SNP markers in Japanese individuals and discovered that specific SNPs in KCNQ1 were associated with type 2 diabetes." (PMID 29259974, 2017). "Genotype analysis relating to KCNQ1 variants and risk of type 2 diabetes (T2D), cardiovascular disease (CVD) and T2D+CVD comorbidity." (PMID 28863213, 2017). "Although these findings need to be verified in a larger population, they supported that KCNQ1 is associated with type 2 diabetes." (PMID 29259974, 2017). "The KCNQ1 locus harbors at least two independent regions of association with type 2 diabetes risk (intron 10 and intron 15), both acting through impaired islet function." (PMID 27857189, 2016). "The current study was designed to investigate the impact of KCNQ1 genetic polymorphism on the efficacy of repaglinide and furthermore to identify the potential mechanism of action in patients with type 2 diabetes." (PMID 27857189, 2016). "In 2008, two Japanese GWAS simultaneously identified the KCNQ1 as a strong susceptibility locus for type 2 diabetes." (PMID 27115357, 2016). "All selected SNPs, with the exception of KCNQ1 rs163171 (the only proxy SNP used in our analysis), were associated with incident type 2 diabetes." (PMID 27623947, 2016). "KCNQ1 has been identified as a susceptibility gene of type 2 diabetes mellitus (T2DM) in Asian populations through genome-wide association studies." (PMID 26678516, 2015). "Surprisingly, the risk alleles for both KCNQ1 polymorphisms substantially increased the odds of type 2 diabetes (rs2237892 OR 1.62, 95% CI 1.01–2.59; rs2237897 OR 2.19, 95% CI 1.25–3.82)." (PMID 25145545, 2014). "Recent reports have shown that variants in KCNQ1 are associated with susceptibility to human type 2 diabetes mellitus." (PMID 23560115, 2013). "TCF7L2 and KCNQ1 were previously considered to be the strongest type 2 diabetes susceptible genes in Caucansians and East Asians, both of which were well replicated in Han Chinese." (PMID 23990951, 2013). "Potassium voltage-gated channel, KQT-like subfamily, member 1 (Kcnq1) is a type 2 diabetes susceptibility gene implicated in reduced beta cell function and decreased insulin secretion." (PMID 23542897, 2013). "In cases of newly diagnosed type 2 diabetes, subjects carrying the KCNQ1 risk allele had lower BMI (β = −0.01738 per for C allele for lnBMI; p = 0.0001), and this correlation remained after multiple test correction (Empirical p = 0.0070)." (PMID 23990951, 2013). "Two independent GWA studies recently performed in Japanese populations identified KCNQ1 as a type 2 diabetes susceptibility gene." (PMID 22403629, 2012).
type 2 diabetes (continued). "We examined the association of these variants within KCNQ1 with type 2 diabetes in a Dutch population, investigated their effects on insulin secretion and metabolic traits and on the risk of developing complications in type 2 diabetes patients." (PMID 22403629, 2012). "We here confirm the association of the KCNQ1 common variants with an increased risk of type 2 diabetes in a Dutch population." (PMID 22403629, 2012). "In conclusion, we here show that common variation in the KCNQ1 gene affect second-phase insulin secretion and confirm the association of the gene with type 2 diabetes in a Dutch population." (PMID 22403629, 2012). "The KCNQ1 variants rs151290, rs2237892, and rs2237895 were genotyped in a total of 4620 type 2 diabetes patients and 5285 healthy controls from the Netherlands." (PMID 22403629, 2012). "This meta-analysis suggests that the rs2237892 and rs2237895 polymorphisms in KCNQ1 are associated with elevated type 2 diabetes susceptibility." (PMID 23133642, 2012). "Common variants in the KCNQ1 gene are associated with type 2 diabetes in a Dutch population, which can be explained at least in part by an effect on insulin secretion." (PMID 22403629, 2012). "We genotyped the KCNQ1 variants rs151290, rs2237892, and rs2237895 in a total of 4,620 type 2 diabetes patients and 5,285 healthy controls." (PMID 22403629, 2012). "Genome-wide association studies in Japanese populations recently identified common variants in the KCNQ1 gene to be associated with type 2 diabetes." (PMID 22403629, 2012). "Recently, genome-wide association studies have identified KCNQ1 as a type 2 diabetes (T2D) susceptibility gene in populations of Asian descent." (PMID 23133642, 2012). "We found that all the genotyped KCNQ1 variants were significantly associated with type 2 diabetes in our Dutch population, and the association of rs151290 was the strongest (OR 1.20, 95% CI 1.07–1.35, p = 0.002)." (PMID 22403629, 2012). "Variants in KCNQ1 have been associated with type 2 diabetes and beta cell function, due to its role as a potassium channel in the pancreatic beta cells." (PMID 21931561, 2011). "Recent genetic studies identified several candidate genes associated with type 2 diabetes, including KCNQ1, while A-FABP also contributed to the development of diabetes mellitus." (PMID 21600061, 2011). "For example, two single nucleotide polymorphisms of the KCNQ1 gene, a well-known type 2 diabetes gene, were associated with higher level of triglycerides and lower levels of HDL-C in Chinese population." (PMID 21092182, 2010). "Similarly, the rs2237892 and rs2237895 polymorphisms of the KCNQ1 gene have been frequently studied in relation to type 2 diabetes mellitus (T2DM) risk and have also been linked to gestational diabetes." (PMID 40365780, 2025). "This study aimed to evaluate the therapeutic effects of luteolin (Lut) on vascular dysfunction in type 2 diabetic rats and explore its underlying mechanisms, particularly its regulation of the myogenic response in thoracic aortic vessels via the Kv7.1 (KCNQ1) channel." (PMID 41035911, 2025). "The KCNJ11 and KCNQ1 gene polymorphisms were associated with type 2 diabetes mellitus and GDM." (PMID 35893051, 2022). "The risk allele of KCNQ1 for type 2 diabetes is also associated with impaired insulin secretion, suggesting that the risk allele might confer susceptibility." (PMID 32722593, 2020). "A recent study suggested that methylation was on the causal pathway between genetic variation in KCNQ1 and type 2 diabetes in later life which supports the former hypothesis." (PMID 30641161, 2019). "Furthermore, we recently reported that a mutation in the Kcnq1 gene, a susceptibility gene for type 2 diabetes, reduced pancreatic β cell mass by epigenetic modulation." (PMID 28886131, 2017).
type 2 diabetes (continued). "Based on all of this evidence, KCNQ1 seems to have been robustly confirmed as a type 2 diabetes susceptibility gene in Han Chinese and may confer type 2 diabetes risk by impaired beta-cell function." (PMID 25587982, 2015). "As 3 SNPs from KCNQ1 showed statistically significantly associated type 2 diabetes in the study, we used logistic regression to determine the independent effects of these SNPs and found that SNP rs2237897 conferred independent risk for type 2 diabetes, as shown in S3 Table." (PMID 25587982, 2015). "Recently Kcnq1 was reported to be a candidate gene for type 2 diabetes susceptibility." (PMID 23560115, 2013). "Meta-analysis of the KCNQ1 rs2237892 polymorphism on type 2 diabetes risk." (PMID 23133642, 2012). "So far, the majority of GWA scans have been performed in populations of European descent, The first GWA studies in East Asians have recently identified single nucleotide polymorphisms (SNPs) in a previously unreported gene, KCNQ1, which were associated with type 2 diabetes susceptibility." (PMID 22403629, 2012). "We could not find any significant relationship of the risk alleles of the KCNQ1 gene with type 2 diabetes complications or mortality." (PMID 22403629, 2012). "Association of the KCNQ1 variants with type 2 diabetes in the Dutch population." (PMID 22403629, 2012). "Meta-analysis of the KCNQ1 rs2237895 polymorphism on type 2 diabetes risk." (PMID 23133642, 2012). "We further investigated whether there was an association between the KCNQ1 gene SNPs and various type 2 diabetes complications and mortality." (PMID 22403629, 2012). "Four single nucleotide polymorphisms (SNPs) (rs2237892, rs2237895, rs2237897, and rs2283228) in KCNQ1 are reported to be associated with type 2 diabetes mellitus (T2DM), possibly caused by a reduction in insulin secretion and higher fasting glucose, but the results are inconsistent." (PMID 20701788, 2010). "For example, two recent GWAS reported common variants on KCNQ1 gene associated with type 2 diabetes mellitus in Japanese population, but European GWAS were unable to identify the associations due to the low allelic frequency of these variants in the population." (PMID 20686608, 2010). "Moreover, the first two independent GWAS in East Asian population added KCNQ1 to the list of type 2 diabetes susceptible gene." (PMID 19862325, 2009). "The potassium voltage-gated channel subfamily Q member 1 (KCNQ1) gene is recognized as a type 2 diabetes mellitus (T2DM) susceptibility gene." (PMID 40671906, 2025). "Potassium voltage-gated channel subfamily Q member 1 (KCNQ1) is one of the strongest susceptibility genes for type 2 diabetes mellitus (T2DM)." (PMID 34750480, 2021). "Thus, the risk allele may influence the development of type 2 diabetes through the increased expression of KCNQ1 in pancreatic β cells." (PMID 32722593, 2020). "The genetic variant rs2237895, located in the Potassium Voltage-Gated Channel Subfamily Q Member 1 (KCNQ1) gene, has been replicated to be associated with type 2 diabetes mellitus (T2DM) susceptibility, but the relationship with lipids is conflicting." (PMID 32016123, 2020). "The aim of this study was to investigate the association of single nucleotide polymorphisms (SNPs) and haplotypes of potassium voltage-gated channel, KQT-like subfamily, member 1 (KCNQ1) with type 2 diabetes (T2D) in Malaysian Chinese subjects." (PMID 22016621, 2011). "Polymorphisms of TCF7L2, IGF2BP2, CDKAL1, KCNQ1, and PPARG genes showed a strong contribution to type 2 diabetes." (PMID 36902173, 2023). "Association of polymorphisms of genes TCF7L2, FABP2,KCNQ1, ADIPOQ with the prognosis of the development of type 2diabetes mellitus." (PMID 35434484, 2022). "Genetic polymorphisms in CDKAL1, CDKN2A/2B, KCNJ11, KCNQ1, and PEPD that we selected as potential effect modifiers were found to be associated with type 2 diabetes in the East Asian population." (PMID 32722593, 2020).